TNF (tumor necrosis factor)
Diseases named in the same sentence as TNF in open-access papers (continued):
Sharing a sentence is not in itself a finding about the gene and the disease.
tuberculosis (continued). "It has been reported that IFN-γ, TNF-α, and IL-12 are critical cytokines in controlling M. tuberculosis infection in mouse model of tuberculosis." (PMID 31801478, 2019). "Contrary to our findings, M. tuberculosis lineage 3 sub strain infections have been associated with different phenotypes for instance, reduced expression of TNFα and IFNγ, reduced growth rate in macrophages, causing cavitary TB, pan sensitivity to anti-TB drugs and causing severe disease." (PMID 31498808, 2019). "One of these studies was an outpatient cohort study that followed participants with HIV-associated tuberculosis and showed that higher pre-ART levels of MCP-1/CCL2, eotaxin, IL-10, TNF-α, and IL-6 were associated with 6-month mortality." (PMID 31276515, 2019). "We report the case of successfully treated a patient with reactive arthritis induced by active extra-articular tuberculosis with a TNF inhibitor after sufficient antitubercular treatment." (PMID 31804308, 2019). "The importance of production activation of IL-2 and TNF-α cytokines for the formation of protective immunity against tuberculosis vaccines was noted and previously actively discussed." (PMID 31683812, 2019). "Recently, ESCMID Study Group Consensus supported LTBC screening before starting of any anti-TNF-α therapy as the standard of care, followed by appropriate anti-tuberculosis therapy." (PMID 31484550, 2019). "TNFα blockade significantly reduced the granuloma index in the group with treated tuberculosis on the 5th and 10th day in the BCG-bead condition (p = 0.015 and p = 0.039) (Wilcoxon)." (PMID 29543912, 2018). "Among 338 patients who received combination tests, 2 patients developed active tuberculosis within 1 year after the TNF inhibitor initiation." (PMID 29975703, 2018). "This live tuberculosis vaccine contains Mycobacterium bovis, known to stimulate the innate immune system by inducing the host to produce TNF that subsequently kills the autoreactive T cells." (PMID 29751683, 2018). "Our data point to a significant inhibitory effect of TNF-α blockade in the group of patients with treated tuberculosis, both in the formation of granuloma and in the production of the cytokines tested." (PMID 29543912, 2018). "This serious health issue initiated the recommendation to screen for tuberculosis with the QuantiFERON Gold Test and to treat infections, even when they are latent, before initiating the anti-TNF treatment." (PMID 29751683, 2018). "In another study, the serum levels of TNF-α in Mycobacterium tuberculosis and non-tuberculosis diseases were measured." (PMID 30588415, 2018). "TNF-α plays a central role in the host defense against microorganisms as demonstrated by the exacerbation or onset of infectious diseases, such as tuberculosis, that occurs in patients with inflammatory diseases that are treated with anti-TNF antibodies." (PMID 29780375, 2018). "The purpose of this study was to determine the importance of TNF-α in protecting against tuberculosis and investigate the rate of production of this cytokine in patients with tuberculosis as compared to the control group." (PMID 30588415, 2018). "Of 476 patients, 2 (0.4%) developed active tuberculosis within 1 year after the initiation of TNF inhibitor." (PMID 29975703, 2018). "Similar to leishmaniasis, a higher incidence of tuberculosis has been described after anti-TNFα therapy." (PMID 30108591, 2018). "For example, mTB has been shown to induce IL-6 in vitro and in vivo and TNF-α plays a critical role in the protective immune response against tuberculosis (TB)." (PMID 30200570, 2018). "Among these cytokines, TNF-α has a prominent role in defense and pathological responses to tuberculosis." (PMID 30588415, 2018). "In conclusion, the findings in this study corroborate earlier reports of the importance of TNF in immune-mediated responses against tuberculosis." (PMID 28280495, 2017).
tuberculosis (continued). "In the M. marinum/zebrafish model of tuberculosis, TNFα excess leads to RIPK1-RIPK3 dependent cell death mediated through phosphoglycerate mutase family member 5 (PGAM5) and mitochondrial reactive oxygen species (ROS) production." (PMID 28892415, 2017). "In Mtb stimulations, percentages and absolute counts of IL-6+ and TNF-α+ monocytes were similar in HIV-tuberculosis patients and controls." (PMID 28369200, 2017). "TNF signaling through TNF receptors (TNFRp55 and TNFRp75) forms an integral component in protective immunity against tuberculosis." (PMID 28280495, 2017). "TNF-α levels were also significantly elevated in sarcoidosis (1139 pg/mL IQR 51.53–2884) vs. tuberculosis (0.1 pg/mL IQR 0.1–0.1, p<0.0001) and healthy volunteer PBMCs (42.29 pg/mL IQR 7.713–103.4, p = 0.027)." (PMID 28114394, 2017). "After 8 weeks of anti-tuberculosis chemotherapy, TNF-α KO mice can experience natural recurrence and death." (PMID 28522990, 2017). "Tuberculosis patients had higher frequencies of TNF-α+ cells compared to all healthy groups, higher frequencies of IFN-γ+-producing cells compared to TBC, and higher frequencies of all Mtb-specific cells compared to HD." (PMID 28871253, 2017). "Tuberculosis of the central nervous system (CNS-TB) is a devastating complication of tuberculosis, and tumor necrosis factor (TNF) is crucial for innate immunity and controlling the infection." (PMID 28280495, 2017). "Current guidelines state that screening for tuberculosis should be performed by history, chest X-ray, tuberculin skin test, and QuantiFERON tests at diagnosis and before starting therapy with anti-TNFα." (PMID 29075289, 2017). "Persistently high levels of released IFN-γ (during the first 3 months) or QFT conversion (after 20–24 months) strongly indicate the development of active tuberculosis in patients undergoing long-term anti-TNFα therapy." (PMID 28886099, 2017). "Both multiple cytokine producing CD4+ T cells as well as TNFα single positive T cells have been identified to discriminate between latent and active tuberculosis." (PMID 28241036, 2017). "TNFα is a pivotal cytokine in tuberculosis, being essential for protection but, paradoxically, at high levels also responsible for the generation of tissue necrosis, increased tissue pathology and enhanced bacterial growth." (PMID 28892415, 2017). "In the M. marinum/zebrafish model of tuberculosis, TNFα excess leads to RIPK1-RIPK3 dependent cell death, involving PGAM5 and mitochondrial ROS production." (PMID 28892415, 2017). "TNFα-single positive T cells were also the strongest predictor of an active tuberculosis in a larger study." (PMID 28241036, 2017). "Percentages of IL-6+ and TNF-α+ neutrophils were lower in HIV-tuberculosis patients (q = 0.01 and q = 0.07, respectively), whereas concentrations of CSF-3, IFN-ɣ, and IL-1RA were higher." (PMID 28369200, 2017). "TNF-α has been demonstrated to be the best anti-mycobacterial immunological factor in humans, it can control tuberculosis by promoting macrophage phagolysosomal fusion and apoptosis." (PMID 28837698, 2017). "Of these 56 AS patients, 23 resumed TNF inhibitors after initiating the anti-tuberculosis treatment (15 patients during anti-tuberculosis treatment and 8 after completion of anti-tuberculosis treatment)." (PMID 27101309, 2016). "In tuberculosis, intercellular networks including TNF-alpha also drive increased MMP gene expression and secretion." (PMID 27658465, 2016). "Baseline features were not different between the early and late resumer groups, including LTBI and history of cured tuberculosis before anti-TNF treatment." (PMID 27101309, 2016). "Although the risk of developing active TB due to the reactivation of LTBI was highest during the first 6–12 months of anti-TNF-α therapy, there was also a possibility of de novo re-infection with Mycobacterium tuberculosis in an area with high or intermediate TB burden like Taiwan." (PMID 27064275, 2016).
tuberculosis (continued). "For example, the functions of membrane TNF has been studied in both listeria and tuberculosis disease models." (PMID 27995986, 2016). "Instances of tuberculosis were treated successfully in our AS patients, even when given concomitantly with TNF inhibitors." (PMID 27101309, 2016). "Ultimately, our nationwide study supports the view that TNF inhibitors can be resumed early in AS patients once active tuberculosis is under control." (PMID 27101309, 2016). "Recommendations are conflicting between delaying and continuing TNF inhibitors on the back of tuberculosis treatment." (PMID 27101309, 2016). "It has also been suggested that HTLV-1 infected patients may, paradoxically, have an increased susceptibility to TB due to impaired TNF-α production in response to M. tuberculosis antigens." (PMID 27643609, 2016). "In the second, a hidden Markov model was used to determine the relative involvements of reactivation of latent infection vs. progression of new infection to the development of active tuberculosis in persons treated with tumor necrosis factor (TNF) antagonists." (PMID 27242697, 2016). "Here, we found favorable long term outcomes of active tuberculosis in AS patients when they resumed TNF inhibitors." (PMID 27101309, 2016). "Sudden onset of pleural effusion after 2 months of discontinuation of etanercept while receiving proper tuberculosis chemotherapy was noted in that patient, eventually, the diagnosis of paradoxical response following discontinuation of TNF inhibitor was made." (PMID 27101309, 2016). "Recent studies have shown that let-7f, another member of the let-7 family, was over-expressed in tuberculosis-infected macrophages that induce tumor necrosis factor (TNF), and IL-1β secretion." (PMID 27157642, 2016). "According to the Korean data of Health Insurance Review and Assessment Service, the incidence of tuberculosis ensuing TNF inhibitors are reported to be 715/100,000 person-years for AS patients and 1143/100,000 person-years for RA patients." (PMID 27101309, 2016). "Clinical information was analyzed about the patients who experienced tuberculosis after exposure to TNF inhibitors." (PMID 27101309, 2016). "Anti-TNF agents used at the time of diagnosis of tuberculosis were infliximab (n = 23, 41.7%), adalimumab (n = 21, 37.5%), etanercept (n = 12, 21.4%) in order of frequency." (PMID 27101309, 2016). "TNFα was used as it is a well known pro-inflammatory cytokine known to be important in the host immunity against tuberculosis and is an inducer of ROS36." (PMID 26876331, 2016). "The overall incidence of tuberculosis is decreasing worldwide, but it remains a concern in patients receiving biologics such as TNF-α inhibitors, interleukin antagonists, and JAK inhibitors." (PMID 27843657, 2016). "Our study was designed to investigate the safety of resuming TNF inhibitors in ankylosing spondylitis (AS) patients who developed tuberculosis as a complication of the use of TNF inhibitors." (PMID 27101309, 2016). "There have been few studies of the outcome and safety of re-administration of TNF inhibitors in AS patients who were infected with tuberculosis due to their previous use." (PMID 27101309, 2016). "These include cytokines which have proven to be critical in the host response against tuberculosis, including IL-12, TNF-α and IL-1β." (PMID 27050308, 2016). "The guidelines of the British Thoracic Society address continuation of TNF inhibitor if clinically indicated and if patients are under appropriate tuberculosis treatment." (PMID 27101309, 2016). "When active tuberculosis occurs in patients with AS on TNF inhibitors, a full course of anti-tuberculosis therapy and withdrawal of the biologics is generally recommended." (PMID 27101309, 2016). "Both theoretical enhancement of anti-tuberculosis drug efficacy and the successful treatment of paradoxical worsening of tuberculosis by addition of TNF inhibitor offer additional grounds for early reusing TNF inhibitor after tuberculosis." (PMID 27101309, 2016).
tuberculosis (continued). "Otherwise baseline features were not different between the groups, including LTBI and history of cured tuberculosis before anti-TNF treatment." (PMID 27101309, 2016). "Fifteen patients resumed TNF inhibitors during anti-tuberculosis treatment (early resumers) and 8 after completion of anti-tuberculosis treatment (late resumers)." (PMID 27101309, 2016). "The frequency of tuberculosis, however, uniquely exceeds that of other serious opportunistic infections in patients treated with this particular TNF-alpha inhibitor." (PMID 27366159, 2016). "Median time to resuming TNF inhibitor from tuberculosis was 3.3 and 9.0 months in the early and late resumers, respectively." (PMID 27101309, 2016). "Patients who develop active tuberculosis following TNF inhibitor use typically discontinue TNF inhibitor use as soon as possible, and reuse of TNF inhibitors has been opposed because of concerns about recurrence of tuberculosis." (PMID 27101309, 2016). "Eight patients (late resumers) restarted TNF inhibitor after completion of anti-tuberculosis treatment while 15 patients (early resumers) restarted during anti-tuberculosis treatment (median duration 9.0 (IQR 7.4–12.6) vs. 3.3 (2.9–4.7) months)." (PMID 27101309, 2016). "Characteristics of five patients who developed active tuberculosis after initiation of anti-TNF therapy." (PMID 25746854, 2015). "Moreover, inhibition of TNF leads to M. tuberculosis dissemination which causes extrapulmonary TB including severe CNS-TB." (PMID 26112704, 2015). "Pereira and colleagues found that, in addition to an enhancement in the production of TNF-α, patients with systemic manifestations of tuberculosis have increased production of IL-10." (PMID 26495323, 2015). "The usefulness of anti-TNF-α therapy has also been demonstrated in two prospective studies that included HIV patients with newly diagnosed tuberculosis in whom an anti-TNF-α inhibitor accelerated the response to tuberculosis treatment." (PMID 26273486, 2015). "It has been well documented that tumor necrosis factor (TNF)-α and matrix metalloproteinases (MMPs) are essential in the pathogenesis of tuberculosis." (PMID 26367274, 2015). "As we have reviewed, the dual activity of TNF as a component of innate immunity and disease pathogenesis has made it inevitable that certain infections, particularly tuberculosis, have a tendency to be exacerbated during long-term anti-TNF therapy." (PMID 26221543, 2015). "Considering that the risk of developing TB due to the reactivation of LTBI was highest during the first 6–12 months of anti-TNF therapy, there was a possibility that some of these patients could develop TB due to recent new infection with M. tuberculosis." (PMID 25746854, 2015). "In conclusion, the findings in this study corroborate earlier reports of the global importance of TNF in immune-mediated responses against tuberculosis and for the first time demonstrate its importance to control M. tuberculosis replication within the CNS." (PMID 26112704, 2015). "TNF-α contributes to the pathogenesis of tuberculosis due to its role in the formation and maintenance of granulomas." (PMID 26359865, 2015). "The critical role of TNF in controlling tuberculosis has been recently illustrated by primary reactivation of latent infection in certain patients under pharmacological anti-TNF therapy for RA." (PMID 25337995, 2014). "TNF, PGE2, and TLR activation have been linked to chronic granulomatous inflammation such as in tuberculosis or granulomatous listeriosis." (PMID 24530056, 2014). "In tuberculosis, some studies have shown that TNFα induces the formation of granulomas and that TNFα deficient mice have a more severe M. tuberculosis infection, possibly due to deficient granuloma formation and thus inability to contain the infection." (PMID 25309534, 2014).
tuberculosis (continued). "The proinflammatory cytokine tumor necrosis factor (TNF)-α is known to play a central role in the formation of granulomas, the sites of protection and pathology in tuberculosis." (PMID 24402617, 2014). "From our literature review, we believe that this short-term usage of TNF inhibitors for will have little effect on the immunity against primary tuberculosis." (PMID 25317081, 2014). "Since the proinflammatory cytokines, IL-1β, IL-6, and TNF-α, contribute to granulomatous inflammation in tuberculosis and other granulomatous diseases, we also examined their levels in granulomas from the two groups of mice." (PMID 25530957, 2014). "Other studies have also shown that individuals with tuberculosis presented elevated TNF-α levels in PBMC culture supernatant compared with controls, and these levels decreased during treatment." (PMID 24558401, 2014). "This review will provide an up-to-date discussion of both the immunology of the TB organism in the human host and the pathophysiologic mechanisms of the TNF-α blockers in the development of secondary (disseminated) tuberculosis." (PMID 25317081, 2014). "Clinicians should consider the possibility of a paradoxical response when the clinical manifestations of non-tuberculosis mycobacteriosis worsen in spite of antimycobacterial therapy or after discontinuation of tumor necrosis factor-α inhibitors." (PMID 24576098, 2014). "A 3 year study by Tubach found 69 cases of tuberculosis (40 in RA) in patients treated with anti-TNFα." (PMID 25414636, 2014). "Briefly, the results demonstrated that blocking CD137:CD137L pathway significantly augmented TNF-α production in tuberculosis patients at 16, 48 and 120 hours." (PMID 23437083, 2013). "While the protective role of IFN-γ in tuberculosis is well established, TNF-α exhibits a very complex network of interactions and many of its functions are still not fully understood." (PMID 23437083, 2013). "Increased mRNA expression of IFN-γ TNF-α, IL-6, IL-8 and IL-12 in tuberculosis granuloma and secretion of cytokines IL-1β, TNF-α and IL-6 in bronchoalveolar lavage fluid from involved sites of pulmonary TB have been reported." (PMID 23308269, 2013). "Regardless of their successful clinical use, long-term treatment with TNF blockers is accompanied by a higher risk of tuberculosis (TB) reactivation and serious infections, whereas the effect of TNF blockers on incidence and/or manifestation of malignancies is discussed controversially." (PMID 23977237, 2013). "In fact, previous studies have shown a decreased production of TNF-α in patients with active disease or with multidrug-resistant tuberculosis." (PMID 23824716, 2013). "Similar to the increase in IFN-γ, we demonstrated an increase in the production of TNF-α over time after the clinical cure of tuberculosis, but in TB-treated patients the increase was significantly higher than in the healthy control group." (PMID 23824716, 2013). "This response has been described in patients with tuberculosis after discontinuation of TNF-α blockers." (PMID 25379301, 2013). "We have previously shown that signaling through the CD137:CD137 ligand (L) pathway interfered with IFN-γ and TNF-α secretion by innate immune cells, while boosting T cell effector functions during tuberculosis." (PMID 23437083, 2013). "HIV coinfection was (nonsignificantly) associated with a reduced frequency of PPD-specific IFN-γ/TNF-α-dual and TNF-α-only responses in active tuberculosis compared with HIV negativity (P = .051 for both)." (PMID 23966657, 2013). "High TNFα gene expression levels were previously reported in granulomas during tuberculosis, in the course of which TNFα is known to represent the dominant cytokine." (PMID 23658779, 2013). "active tuberculosis was associated with an increased frequency of mono- or dual-functional CD4+ and CD8+ M. tuberculosis-specific T cells that secrete IFN-γ and/or TNF-α making these subsets potential biomarkers of disease activity." (PMID 23966657, 2013).